L1CAM (L1 cell adhesion molecule)
Diseases named in the same sentence as L1CAM in open-access papers (continued):
Sharing a sentence is not in itself a finding about the gene and the disease.
tumor (continued). "This study, furthermore, demonstrated that L1CAM contributes to tumor dissemination and chemoresistance as well as to CSC-driven generation of organoids." (PMID 34645505, 2021). "Organoids and tumours, surviving post chemotherapy, are highly enriched for L1CAM expression, and the combination of irinotecan and L1CAM knockdown is more potently cytotoxic than either treatment alone." (PMID 33673710, 2021). "L1CAM silencing in SKOV3 cells almost abolished tumor initiation, while the latter was significantly enhanced in L1CAM-transfected Ov90 cells." (PMID 34645505, 2021). "L1CAM increased 4-fold the frequency of tumor initiating cells, confirming its ability to enhance the tumorigenic potential of OC cells." (PMID 34645505, 2021). "To determine if STAT3 is also required for L1CAM-induced tumor initiation, we injected immunodeficient mice with Ov90-mock and Ov90-L1CAM cells and treated them with Napabucasin starting three days after injection." (PMID 34645505, 2021). "In order to evaluate the impact of the L1CAM expression on tumor growth, we knocked-down (KD) its expression in PDO#2 by shRNAs." (PMID 33897875, 2021). "We observed that GFP-positive clusters of invasive cells at the tumor invasion front expressed high levels of L1CAM (A′)." (PMID 35008571, 2021). "Together with the other findings described here, these data imply that L1CAM not only orchestrates the tumor-initiating function of OCSC, but it also fuels OCSC-driven chemoresistance." (PMID 34645505, 2021). "This review further demonstrates a focus only on the tumor suppressor role of L1CAM out of the adhesion molecule family members." (PMID 33928036, 2021). "Human L1CAM-specific CAR T cells harboring short- or long-spacer CAR constructs with CD28 co-stimulation lysed significantly more tumor cells than CAR T cells using 4-1BB signaling at each time point analyzed." (PMID 33801448, 2021). "L1CAM-specific CAR T cells were more strongly activated in the bioprinted 3D tumor model, but induced less IFNG release than in 2D cocultures." (PMID 34267756, 2021). "L1CAM-targeting short spacer-CD28/ζ CAR T cells expanded the most at the tumor site and induced initial tumor regression." (PMID 33801448, 2021). "L1CAM expression can induce IL-1β secretion and NF-κB activation not only in tumor cells but also in immune cells." (PMID 34659539, 2021). "In the tumor microenvironment, L1CAM expression correlated with Treg infiltration in ESCC by affecting CCL22 secretion." (PMID 33710805, 2021). "Together, these results indicate that L1CAM recruits Tregs to tumor sites, thereby promoting tumor progression by regulating CCL22 secretion in vitro and in vivo." (PMID 33710805, 2021). "Xenograft studies were performed in nude mice to evaluate the effects of L1CAM on tumor growth and regulatory T cell (Treg) recruitment." (PMID 33710805, 2021). "The addition of anti-L1CAM inhibited tumor growth much more than chemotherapy alone and increased apoptosis." (PMID 32429448, 2020). "In summary, various studies conducted on different tumor types have shown the remarkable potential of L1CAM-targeting strategies for the design of innovative antitumor therapies." (PMID 32429448, 2020). "In this tumor type, L1CAM shows a wide range of expression, from a small fraction of cancer cells to high levels in most of the tumor mass." (PMID 32429448, 2020). "Previous publications demonstrated the regulation of L1CAM through the Wnt/β-catenin signaling and nuclear β-catenin appears to co-localize with L1CAM in tumor sections." (PMID 31952346, 2020). "A very recent study has provided compelling evidence that high L1CAM expression marks a subpopulation of CRC cells with tumor propagation, metastasis-initiating and chemoresistance features." (PMID 32429448, 2020).
tumor (continued). "This role of monocytes in the response to L1CAM-mediated immunotherapy would be consistent with a crosstalk between L1CAM and the tumor immune microenvironment." (PMID 32429448, 2020). "We also found that CD171/L1CAM and mTOR were increased at progression in tumor biopsies from two matched cases of patients receiving targeted therapy with BRAFi." (PMID 33082316, 2020). "For example, in tumor endothelium L1CAM promotes endothelial-to-mesenchymal transition (EndMT), a phenomenon reminiscent of EMT." (PMID 32429448, 2020). "Isolated GSCs were characterized by the expression of the GSC markers (SOX2, OLIG2, CD133, L1CAM) and functional assays including serial neurosphere formation assay, in vitro cell differentiation assay and in vivo limiting dilution tumor formation assay." (PMID 32541784, 2020). "TGF-β1 modulates the expression of L1 cell adhesion molecule (L1CAM), but its role in tumour progression still remains controversial." (PMID 32291413, 2020). "Restoring L1CAM expression diminishes stemness and thereby sensitise tumours for chemotherapy, which should result in more lasting responses to treatment." (PMID 32291413, 2020). "SKOV3ip L1CAM+/CD133+ cells showed the highest tumor take in comparison to all other cell populations." (PMID 31952346, 2020). "Based on their MFIs, GD2, HER2, B7H3, CSPG4, L1CAM (CD171), and Lewis Y were chosen as tumor targets for further in vitro screening." (PMID 33303017, 2020). "The expression of L1CAM can promote the remodeling of extracellular matrix and enhance the chemotaxis of tumor cells to the extracellular matrix, both of which promote tumor invasion and metastasis 18-20,23." (PMID 32742486, 2020). "The expression pattern of L1CAM in many different cancer types as well as its pivotal role in diverse tumor-related cellular processes, including cancer stemness, makes it a suitable target for antitumor therapies." (PMID 32429448, 2020). "Immediately after treatment mice were sacrificed, tumours were measured, and then disaggregated and stained for L1CAM." (PMID 32291413, 2020). "L1CAM in cancer promotes motility and invasiveness, supporting aggressive tumor growth, metastasis and chemoresistance and in many human cancers, such as ovarian and endometrial carcinoma, frequently correlates to poor prognosis and advanced tumor stage." (PMID 31952346, 2020). "The treatment with 177Lu-NOTA-cA10-A3 of mice xenografted with L1CAM-overexpressing SCK-L1 cells reduced tumor volume by promoting cell apoptosis and reducing cell proliferation." (PMID 32429448, 2020). "As the characteristics of extracellular and intracellular domains, L1CAM has been seemingly involved in tumor proliferation, migration, and invasion." (PMID 32509846, 2020). "Many lines of experimental and clinical evidence support the potential relevance of L1CAM in the management of tumor patients." (PMID 32429448, 2020). "In another study, decreased miR-34a-5p expression upregulated the L1CAM level in EC cell lines and tumours." (PMID 32842533, 2020). "We provided in vivo evidence that small L1CAM+/CD133+ cell populations are capable of tumor initiation with fast tumor growth." (PMID 31952346, 2020). "L1CAM is overexpressed in a variety of cancers, and has been shown to be capable of exerting both tumor and metastasis-promoting effects." (PMID 33196691, 2020). "L1CAM expression in cancer supports motility and invasion, promoting aggressive tumor growth and metastasis formation." (PMID 32257947, 2020). "The contribution of L1CAM to tumor development can also occur via the modulation of stemness-related properties within the tumor microenvironment, which in turn modulates cancer cell behavior in a non-autonomous manner." (PMID 32429448, 2020). "Of note, L1CAM was consistently detected at the invasive front of OC, supporting its role in tumor invasion." (PMID 32429448, 2020).
tumor (continued). "We propose that L1CAM belongs to a new type of cancer genes that can act both as an oncogene and as a tumour suppressor, depending on the cellular/genomic context." (PMID 32291413, 2020). "Our data provide functional proof and mechanistic insights for the tumour-suppressive function of L1CAM via reducing stemness." (PMID 32291413, 2020). "Yet the expression pattern and the role of the molecule in this subpopulation of tumor cells provide the rationale for assessing the impact of L1CAM-targeted treatments on CSC function." (PMID 32429448, 2020). "ShRNA targeting of L1CAM expression in vivo suppressed tumor growth and increased animals’ survival." (PMID 32722427, 2020). "These integrins bind to L1-CAM found on endothelial cells and mediate a more invasive tumor cell phenotype." (PMID 30657059, 2019). "L1CAM protein expression was mainly observed in the membrane and occasionally in the cytoplasm of tumour cells." (PMID 31754264, 2019). "Since these cellular processes influence tumor angiogenesis, cancer growth and metastasis, L1CAM has emerged as a potential target for tumor vascular-specific therapies." (PMID 30829570, 2019). "Downregulation of L1CAM resulted in significant inhibition of tumour cell growth at 48 and 72 h after L1CAM siRNA transfection." (PMID 31754264, 2019). "Intriguingly, numbers of peritoneal tumours following L1CAM siRNA transfection were drastically fewer than in mice transfected with control siRNA." (PMID 31754264, 2019). "In contrast, integrin αVß3, representing a binding partner for L1-CAM, is expressed on various types of tumor cells." (PMID 30657059, 2019). "It is reported that L1CAM-SV, which lacks exon 2 and 27, is co-expressed with L1CAM-FL, with L1CAM-SV being the dominant form in many tumor types." (PMID 31455004, 2019). "In general, the methodology of these studies involved screening of expression of patient samples and tumor cell lines across a wide array of mostly carcinomas, flanked by overexpression of L1CAM-FL or siRNA-mediated knockdown (KD) in vitro and in vivo." (PMID 31455004, 2019). "The studies covered in the review demonstrate abundant in vitro evidence for indirect tumor promoting effects of L1CAM ectodomains, and the challenge will be to understand its implications in patients." (PMID 31455004, 2019). "In the last years, L1-cell adhesion molecule (L1CAM), a transmembrane protein of the immunoglobulin family that has been implicated in promoting tumor cell proliferation, migration, invasion, and metastasis, has been investigated in EC." (PMID 29980240, 2018). "While L1CAM-positive tumours clearly have worse outcomes, we support maintaining the original 4 TCGA/ProMisE tumour subgroups." (PMID 30050154, 2018). "Of positive tumours, 59/452 (13.1%) showed moderate L1CAM staining (score 2, > 10–50%), and 38/452 (8.4%) showed strong L1CAM expression (score 3, > 50%)." (PMID 30050154, 2018). "There were relatively few L1CAM-positive tumours, which limited our power to study additional variables in the model using all four ProMisE subgroups." (PMID 30050154, 2018). "Remarkably, it was previously reported in primary tumor sections an inverse correlation between L1CAM protein and miR-34a expression." (PMID 29980240, 2018). "HR for L1CAM-positive tumours was 1.33 (CI 0.77–2.22; p = 0.3) for OS and 2.05 (CI: 1.00–4.10; p = 0.05) for DSS." (PMID 30050154, 2018).
tumor (continued). "L1CAM was positive in 8/47 (17.0%) cases distributed as follow: 10% of tumor cells (2 cases), 20% (1 case), 30% (1 case), 40% (1 case), 80% (2 cases), and 90% (1 case)." (PMID 30557309, 2018). "A number of studies demonstrated that the effect of different anti-L1CAM antibodies on tumor cells can be utterly varying (from inhibition to stimulation of tumor cells), which is mainly due to the particular epitope that the antibody binds." (PMID 30116755, 2018). "In contrast, anti-L1CAM RIT alone or in combination with MK1775 markedly reduced tumour growth in comparison to the control group (PBS) and the MK1775 treated mice." (PMID 30253737, 2018). "Expression of L1CAM in cancer tissues and cultured tumor cells in most cases correlates with poor clinical prognosis and a late stage of the disease." (PMID 30116755, 2018). "The most informative cut-off value in these different tumor types was >10% of L1CAM positive tumor cells, as determined by immunohistochemistry." (PMID 29152102, 2017). "In our experimental models, depletion of Mint3 or L1CAM in fibroblasts decreased tumour growth of co-injected cancer cells in mice." (PMID 28504692, 2017). "One suggested mechanism through which L1CAM influences tumor progression and metastasis formation is epithelial-mesenchymal transition (EMT)." (PMID 29152102, 2017). "In this study, we focused on the tumour growth function of Mint3 in fibroblasts, and revealed that Mint3-mediated L1CAM expression in fibroblasts promoted cancer cell proliferation and tumour growth." (PMID 28504692, 2017). "L1CAM-expressing Mint3 KO MEFs significantly increased tumour growth of co-injected MDA-MB-231 and A431 cells compared with mock expressing cells, indicating that fibroblast Mint3 promoted tumour growth at least in part by inducing L1CAM expression." (PMID 28504692, 2017). "Although the knowledge in this regard is quite limited, L1CAM represents a promising therapeutic target also in the context of tumor vasculature." (PMID 28134764, 2017). "The prognostic value of L1CAM was stronger than currently established prognostic factors, such as status of resection margins and tumor size." (PMID 29152102, 2017). "Regarding mechanism of action, in this study we observed that Ab417 was internalized into L1CAM-expressing cells and decreased membrane L1CAM level in vitro and in vivo, while it inhibited tumor cell proliferation in vivo." (PMID 28166242, 2017). "In 80 cases (21%), more than 10% of the tumor cells were L1CAM positive, of which 35 cases (9%) showed staining in more than 50% of the tumor." (PMID 29152102, 2017). "The translational implications of this finding are supported by the observation that not only genetic ablation, but also antibody-mediated neutralization of L1CAM normalizes the tumor vasculature." (PMID 28134764, 2017). "While, as discussed in the previous section, tumor cell-derived L1CAM mediates their binding to the vasculature, it is clear that a similar function is also carried out by L1CAM expressed in the vascular counterpart." (PMID 28134764, 2017). "As MEFs, CAFs also promoted cancer cell proliferation in vitro, and tumour growth via Mint3 and L1CAM." (PMID 28504692, 2017). "Here we showed that L1CAM not only promoted static cell-cell adhesion that keeps tumor cells together, but also RCC cell migration and invasion." (PMID 28428626, 2017). "L1CAM promotes proliferation, migration, invasion, and survival of tumor cells through L1CAM homophilic interaction and/or heterophilic interactions with other cell surface molecules." (PMID 28166242, 2017).
tumor (continued). "In glioma cells, upregulation of ADAM10 at the tumor edges was shown to result in increased soluble L1CAM, interacting with integrin receptors, activation of focal adhesion kinases, and focal complex turnover, all resulting in enhanced migration." (PMID 28260841, 2017). "For survival analysis, patients were stratified according to L1CAM expression and percentage of vimentin expressing tumor cells." (PMID 29152102, 2017). "We previously developed a fully human anti-L1CAM mAb (Ab417, IgG1) that cross-reacts with mouse L1CAM, and validated that Ab417 inhibits tumor growth in a Choi-CK xenograft nude mouse model." (PMID 28166242, 2017). "We here provide an overview on tumor angiogenesis and antiangiogenic therapies and summarize the current knowledge on the biological role of L1CAM in cancer vasculature." (PMID 28134764, 2017). "Several markers have been defined to isolate GICs from the bulk of the tumor: CD133, encoded by PROM1, CD44, L1CAM or ITGA6." (PMID 29088733, 2017). "As elegantly reviewed elsewhere, the use of anti-L1CAM antibodies that block its pro-malignant function, either alone or in combination with cytotoxic drugs, frequently resulted in dramatic inhibition of tumor growth and/or dissemination." (PMID 28134764, 2017). "In this study, we showed that Mint3-mediated L1CAM expression in fibroblasts promoted tumour growth." (PMID 28504692, 2017). "Regarding the mechanism of action, Ab417 was internalized into the tumor cells and thereby down-regulated membrane L1CAM, and inhibited tumor growth by reducing tumor cell proliferation in vivo." (PMID 28166242, 2017). "L1CAM-depleted CAFs decreased in vitro proliferation and tumour growth of co-cultured/co-injected MDA-MB-231 and A431 cells, similarly to Mint3-depleted CAFs." (PMID 28504692, 2017). "Consistent with our findings, antibody-mediated neutralization of L1CAM inhibited the migratory and remodeling capacity of tumor-derived ECs." (PMID 28134764, 2017). "We previously developed a human mAb (Ab417) having high affinities for both human and mouse L1CAM and validated its anti-tumor activity in an ICC xenograft nude mouse model." (PMID 28166242, 2017). "In cases 6 and 7, more than 10% L1CAM expression was observed in only one out of three tumour blocks." (PMID 28424422, 2017). "In normal adult tissue, L1CAM is only expressed by nerve tissue, leukocytes and renal tubules of the kidney, whereas in cancer it has also been reported to be expressed on tumour cell surface." (PMID 27028855, 2016). "From the Leiden cohort, 103 patients were included, and tumour sections from all patients were analysed for L1CAM." (PMID 27028855, 2016). "L1CAM is described in various processes contributing to tumour progression, such as differentiation, proliferation, migration, invasion and tumour cell adhesion." (PMID 27074785, 2016). "The meta-analysis presented herein is the first comprehensive description of all reported studies investigating the impact of L1CAM expression in human tumours on prognosis." (PMID 27833079, 2016). "L1CAM expression was observed at the invasive front or in spray-patterned parts of 17% of the tumours." (PMID 27028855, 2016). "Patients with L1CAM expressing tumours have a significantly worse 5 year disease specific survival compared to patients with normal L1CAM expression (80% vs 64%)." (PMID 27028855, 2016). "The functional role of L1CAM in tumour cell invasion and motility primarily depends on ectodomain cleavage from membrane proximal proteolysis, binding partner alterations and integrin binding." (PMID 27833079, 2016). "An increased L1CAM expression lead to a lower expression of caspase-8 and thereby increased apoptotic resistance of tumor cells." (PMID 27174921, 2016). "The 5 year overall and disease specific survival was significantly worse for patients with L1CAM positive tumours (46.1% vs 63.6%, log rank P=.014 and 63.8% vs 80.0%, log rank P=.018)." (PMID 27028855, 2016).